B4GALNT2 (beta-1,4-N-acetyl-galactosaminyltransferase 2 (SID blood group))
Description:
Beta-1,4 N-acetylgalactosaminyltransferase involved in the biosynthesis of Sd(a) histo-blood group antigen. Catalyzes the transfer of N-acetylgalactosamine (GalNAc) group in a beta-1,4-linkage from UDP-GalNAc to the galactose residue of NeuAcalpha2->3Gal-R to form Sd(a) glycan epitope GalNAcbeta1->4(NeuAcalpha2->3)Gal-R. The Sd(a) epitope is carried in O- and N-linked glycoproteins and glycolipids, including O-linked core 1 structures on GYPA/glycophorin, SLC4A1 and SLC29A1 in erythrocytes, N-linked glycans attached to the Tamm-Horsfall glycoprotein UMOD/uromodulin in renal fluids, O-linked core 3 glycans on mucins in colon and neolactosides in gastric mucosa. Confers protection against influenza A virus strains that attach to NeuAcalpha2->3-carrying host receptors. Modifies N-glycan chains on host receptors and prevents virus entry into cells.
Synonyms: GALGT2; Sda; Cad; B4GALT
Tractability: Antibody: UniProt predicts a signal peptide or a membrane-spanning region.
Gene: Protein-coding gene on chromosome 17 (49,132,460 to 49,178,647, forward strand). Ensembl gene ENSG00000167080.
Subcellular location: Golgi apparatus, trans-Golgi network membrane (Isoform 1); Cytoplasmic vesicle membrane; Golgi apparatus, trans-Golgi network membrane (Isoform 2)
Pathways (Reactome):
Metabolism: Lewis blood group biosynthesis
Metabolism of proteins: Asparagine N-linked glycosylation
Gene Ontology:
Molecular function: acetylgalactosaminyltransferase activity; N-acetylneuraminylgalactosylglucosylceramide beta-1,4-N-acetylgalactosaminyltransferase activity; protein binding; hexosyltransferase activity
Biological process: negative regulation of cell-cell adhesion; UDP-N-acetylgalactosamine metabolic process; oligosaccharide biosynthetic process; protein N-linked glycosylation; UDP-N-acetylglucosamine metabolic process; carbohydrate derivative metabolic process
Cellular component: cytoplasmic vesicle membrane; Golgi membrane; membrane; Golgi apparatus
Genetic constraint (gnomAD): Loss-of-function variants: 42 observed, 48.86 expected, observed/expected ratio (o/e) 0.86, 90% interval 0.67 to 1.11. The upper end of that interval is the gene's LOEUF score, 1.11, which puts it in group 4 of 6, group 1 being the genes least tolerant of losing a copy. Missense variants: 521 observed, 585.35 expected, observed/expected ratio (o/e) 0.89, 90% interval 0.83 to 0.96. Synonymous variants: 224 observed, 236.39 expected, observed/expected ratio (o/e) 0.95, 90% interval 0.85 to 1.06.
Homologues: Orthologues: chimpanzee B4GALNT2 (98% identical), macaque B4GALNT2 (94% identical), dog B4GALNT2 (82% identical), rabbit B4GALNT2 (79% identical), rat B4galnt2 (75% identical), guinea pig B4GALNT2 (74% identical), mouse B4galnt2 (74% identical), tropical clawed frog b4galnt2 (48% identical), zebrafish b4galnt2.2 (37% identical), zebrafish b4galnt2.1 (36% identical), zebrafish zmp:0000001331 (35% identical). Paralogues in human: B4GALNT1 (42% identical).
Diseases named in the same sentence as B4GALNT2 in open-access papers:
B4GALNT2 is named in the same sentence as 37 diseases in open-access papers, as found by Europe PMC text mining. Sharing a sentence is not in itself a finding about the gene and the disease. The quoted sentences say what the papers report.
colon cancer (15 papers, 2017 to 2025). "On the one hand, in colon cancer, expression of B4GALNT2 gene was causally associated with a better prognosis, where B4GALNT2/Sda inhibited the stemness-associated malignant phenotype." (PMID 34589428, 2021). "Recently an enzyme catalyzing glycosylation, B4GALNT2, has been associated with increased susceptibility to Salmonella infection, while its expression has been reported to be downregulated in colon cancer compared with normal mucosa." (PMID 28903406, 2017). "It has been reported that in colon cancer cells lines, B4GALNT2 promoter methylation is associated with a very low level of mRNA expression." (PMID 28481247, 2017). "The Sda carbohydrate epitope and its biosynthetic B4GALNT2 enzyme are expressed in the healthy colon and down-regulated to variable extents in colon cancer." (PMID 36835549, 2023). "A high level of B4GALNT2 expression is associated with longer overall survival in the COAD cohort and attenuation of malignant phenotype in colon cancer cell lines." (PMID 35565254, 2022). "Another study found methylation of the B4GALNT2 gene in the majority of gastric and colon cancer cell lines." (PMID 34771437, 2021). "Which insights do these data provide into the role of methylation in the general downregulation of B4GALNT2 mRNA observed in colon cancer?" (PMID 33919332, 2021). "High level of B4GALNT2 gene expression appears to be a good marker of prognosis in colon cancer; however, the molecular mechanisms regulating these carbohydrate antigens’ expression are still poorly understood." (PMID 34397142, 2021). "In fact, treatment of different colon cancer cell lines with the methylation inhibitor 5-aza-2′-deoxycytidine resulted in a partial activation of B4GALNT2 expression." (PMID 33919332, 2021). "In fact, while the enzyme activity of both Sda and B4GALNT2 was higher in the poorly differentiated cells of the colonic crypt, B4GALNT2 expression increased upon differentiation of the human colon cancer Caco2 cells." (PMID 34771437, 2021). "TCGA data showed a clear tendency towards an inverse relationship between some of these miRNAs and B4GALNT2 in colon cancer tissues." (PMID 34771437, 2021). "More recently, we have shown that in the colon cancer cell line LS174T that constitutively expresses sLex/a, B4GALNT2 reduced stemness-associated features, in particular the ability to grow in poor adherence." (PMID 34771437, 2021). "This cell line was chosen because it is devoid of B4GALNT2 activity and of cognate Sda antigen (like the vast majority of colon cancer cell lines) and is one of the few CRC cell lines expressing the sLex antigen." (PMID 32290493, 2020). "As early as 2003, human full-length clones of the B4GALNT2 gene were obtained from the human colon cancer cell line Caco-2." (PMID 30241280, 2018). "The B4GALNT2 gene was found to be methylated in about half of the gastric cancer cases examined, and in the majority of gastric and colon cancer cell lines." (PMID 28481247, 2017). "Both the Sda antigen and B4GALNT2 are highly expressed in normal colon and down-regulated in colon cancer." (PMID 28241499, 2017). "In fact, while in colon cancer tissues (where B4GALNT2 levels are low) sLex levels correlate with FUT6 expression, in normal colon (where B4GALNT2 is high), they correlate with the FUT6/B4GALNT2 ratio." (PMID 28241499, 2017). "The expression level of B4GALNT2 has been proposed as a prognostic marker for colon and breast cancer and its manipulation might represent a therapeutic perspective for colon cancer and muscular dystrophy." (PMID 40667754, 2025). "Consequently, B4GALNT2 seems to inhibit both malignant properties and stemness of colon cancer cells, independently of SLex expression." (PMID 34397142, 2021). "In general, methylation of the island and of the northern and southern shore positions in colon cancer is closely associated with low or no B4GALNT2 transcription." (PMID 34771437, 2021).
colon cancer (continued). "However, our recent work has shown that B4GALNT2 expression decreases malignancy and stemness in different models of colon cancer cell lines, independently of sLex inhibition." (PMID 33919332, 2021). "Forced B4GALNT2 expression reduced the malignancy and stemness of colon cancer cells." (PMID 33919332, 2021). "Here, we investigated the clinical and biological importance of B4GALNT2 in colon cancer." (PMID 32290493, 2020). "In a preliminary survey of TCGA, we noticed that among various glycosyltransferases involved in colon cancer, B4GALNT2 displayed a very good predictive potential in that patients retaining higher levels of B4GALNT2 mRNA displayed a much longer overall survival." (PMID 32290493, 2020). "In this study, we show for the first time that in a large cohort of colon cancer samples, the mRNA of B4GALNT2 is dramatically down-regulated compared with normal tissue, consistent with previous observations of a reduced B4GALNT2 enzymatic activity in CRC tissues." (PMID 32290493, 2020). "The two colon cancer cell lines were chosen as recipients of FUT6 and B4GALNT2 enzymes for two reasons." (PMID 32911675, 2020). "The molecular bases of B4GALNT2 downregulation in colon cancer tissues and cell lines have not been fully elucidated, although methylation appears to plays a role." (PMID 33919332, 2021). "The molecular bases of the reduced B4GALNT2 expression in colon cancer are not completely clear, although the methylation of the B4GALNT2 promoter certainly plays a role." (PMID 32911675, 2020). "This work provides evidence that this is not the case because the tumor restraining effect of B4GALNT2 in CRC is largely independent of sLex inhibition but is due to intimate changes of the colon cancer cell biology." (PMID 32911675, 2020). "Owing to the clear association between high B4GALNT2 and better prognosis, the impact of B4GALNT2 expression on the malignant phenotype of a colon cancer cell line was studied using, as a model, LS174T cells transfected with the short form of B4GALNT2 or mock-transfected." (PMID 32290493, 2020).
breast carcinoma (8 papers, 2017 to 2025). "Using RT-qPCR, we examined the relative expression level of gene B4GALNT2 mRNA in five different breast cancer cell lines, namely MDA-MB-231 (ER-/PR-/HER2-), T47D (ER+/PR+/HER2-), MCF7 (ER+/PR+/HER2-), SK-BR-3 (ER-/PR-/HER2+) and HCC1937 (ER-/PR-/HER2-)." (PMID 34589428, 2021). "Results of the analysis of differential expression of B4GALNT2 gene in breast cancer and adjacent normal tissues indicated that this gene was highly expressed in the former." (PMID 34589428, 2021). "We conducted genetic analysis of TCGA database for patients of breast cancer, where 1094 breast cancer and normal tissues were analyzed for expression of B4GALNT2 gene." (PMID 34589428, 2021). "A possible involvement of B4GALNT2 in the biology and clinic of breast cancer (BRCA) has only recently emerged." (PMID 34771437, 2021). "To further corroborate that B4GALNT2 is highly expressed in breast cancer cells, we examined the relative expression level of gene B4GALNT2 mRNA in five different breast cancer cell lines, where high levels of the corresponding mRNA were found." (PMID 34589428, 2021). "A recent study reported a systemic upregulation of B4GALNT2 in an experimental model of breast cancer." (PMID 34771437, 2021). "B4GALNT2 is down-regulated in colorectal and gastric cancers and elevated in breast cancer, and in CM, we report for the first time that it may act as a risk factor influencing patient prognosis." (PMID 37422626, 2023). "Thus, in the present paper, we conducted genetic analysis of TCGA database for breast cancer and normal tissues, where it was found that expression of B4GALNT2 gene in breast cancer tissues was higher compared to adjacent normal tissues." (PMID 34589428, 2021). "Compared with adjacent healthy tissues, B4GALNT2 gene is highly expressed in breast cancer tissues." (PMID 34589428, 2021). "B4GALNT2 may promote the proliferation and metastasis of breast cancer cells by interacting with HLA-B protein." (PMID 34589428, 2021). "Thus, the B4GALNT2 gene can be used as an indicator to judge the prognosis of breast cancer patients and has the potential as a new therapeutic target." (PMID 34589428, 2021). "The Sda biosynthetic enzyme B4GALNT2 undergoes downregulation in colorectal (CRC) and stomach cancer, while it is ectopically expressed by a minority of breast cancer (BRCA) patients." (PMID 34771437, 2021). "However, high B4GALNT2 expression correlated with a worse prognosis in the BRCA cohort and increased malignancy in breast cancer cell lines." (PMID 35565254, 2022). "A comparison was made between 1094 breast cancer and non-tumor tissues to determine the differential expression of B4GALNT2 gene, and the corresponding volcano map was constructed." (PMID 34589428, 2021). "It was found that B4GALNT2 gene is overexpressed in breast cancer tumor tissues compared to non-tumor adjacent ones." (PMID 34589428, 2021).
gastric cancer (7 papers, 2014 to 2023). A primary or metastatic malignant neoplasm involving the stomach. "This is in agreement with a previous study showing that differential B4GALNT2 promoter methylation is only partially correlated with gene expression in gastric cancer cell lines." (PMID 33919332, 2021). "In vitro experiments have shown that forced expression of B4GALNT2 in colon and gastric cancer cell lines strongly reduced sLex/a expression." (PMID 34771437, 2021). "The downregulation of B4GALNT2 in gastric cancer was documented successively." (PMID 34771437, 2021). "Cancer-dependent modulation of B4GALNT2 was reported by numerous studies in CRC and by a few in gastric cancer." (PMID 34771437, 2021). "B4GALNT2 and ST3GAL6 have been found to be epigenetically silenced in colon and gastric cancer cells and shown to be re-expressed after 5-Aza treatment." (PMID 25294702, 2014). "According to TCGA data, B4GALNT2 is expressed in the gastric mucosa by only a few cases, while it is virtually not expressed in gastric cancer, with few exceptions." (PMID 34771437, 2021). "However, the low level of expression in gastric cancer tissues did not allow investigating the relationship between B4GALNT2 expression and methylation or clinical features using TCGA data." (PMID 34771437, 2021). "Additionally, although the role of B4GALNT2 (Beta-1,4-N-Acetyl-Galactosaminyltransferase 2) in LUAD has not been investigated, it has been observed to be highly related to gastric cancer metastasis." (PMID 33195688, 2020).
colorectal cancer (5 papers, 2016 to 2021). A primary or metastatic malignant neoplasm that affects the colon or rectum. "Dramatic loss or down regulation of B4GALNT2 has been shown in colorectal cancer, leading to increased formation of the sialyl-Lewis antigens, which have been employed as biomarkers for colorectal cancer." (PMID 30072673, 2018). "Preliminarily, a list of miRNA potentially targeting B4GALNT2 in colorectal cancer was obtained from the CSmiRTar database." (PMID 33919332, 2021). "In colorectal cancer, B4GALNT2 is generally downregulated, but patients displaying higher expression survive longer." (PMID 34771437, 2021). "Forced expression of B4GALNT2 in colorectal cancer cell lines modulates the transcriptome towards lower malignancy, reducing stemness." (PMID 34771437, 2021). "The dramatic downregulation of B4GALNT2 expression in colorectal cancer tissues was formerly reported in 1989, successively confirmed and found to be largely due to a reduced mRNA expression." (PMID 34771437, 2021). "B4GALNT2 promoter DNA hypermethylation in colorectal cancer correlated with decreased gene expression and the absence of the glycan Sda on the cell surface." (PMID 27429195, 2016). "Thus, B4GALNT2 is a marker of better prognosis and a cancer-restraining enzyme in colorectal cancer, with a therapeutic potential." (PMID 34771437, 2021). "The expression of B4GALNT2 is very high in normal colonic mucosa but undergoes a dramatic downregulation in colorectal carcinoma (CRC)." (PMID 33919332, 2021). "Background: glycosyltransferase B4GALNT2 and its cognate carbohydrate antigen Sda are highly expressed in normal colon but strongly downregulated in colorectal carcinoma (CRC)." (PMID 33919332, 2021).
virus infection (3 papers, 2022 to 2025). "Following viral infection, we showed that human B4GALNT2 reduced infection of two AIV subtypes and NDV at 12-, 24-, and 36-hours post-infection." (PMID 37483287, 2023). "Therefore, the inhibitory effect of virus infection in engineered chicken cells could be dominantly mediated by human B4GALNT2 expression." (PMID 37483287, 2023). "In this study, we demonstrate that the roles of host genes involved in productive virus infection can be identified either through either knockout, as exemplified by CMAS, or through overexpression, as for B4GALNT2 and ADAR1." (PMID 39887213, 2025). "Although the expression of human B4GALNT2 did not completely block viral infection, it demonstrated the ability to suppress multiple viruses, including AIV and NDV, with a preference for α-2,3-linked sialic acid." (PMID 37483287, 2023).
Duchenne muscular dystrophy (2 papers, 2021). Duchenne muscular dystrophy (DMD) is a neuromuscular disease characterized by rapidly progressive muscle weakness and wasting due to degeneration of skeletal, smooth and cardiac muscle. "We should also point out that there is an ongoing clinical trial (phase I/IIa) for B4GALNT2 gene therapy for treatment of duchenne muscular dystrophy." (PMID 34589428, 2021).
intestinal infection (2 papers, 2015 to 2023). "To investigate the role of variant host B4galnt2 expression in the context of intestinal infection, we challenged mice engineered to express B4galnt2 in various tissue-specific patterns with a mouse model of the intestinal pathogen Salmonella enterica serovar Typhimurium (S. Typhimurium)." (PMID 26133982, 2015). "Thus, a complex scenario including B4galnt2-dependent changes in microbial communities, vascular immune phenotypes, bleeding tendencies and susceptibility to intestinal infections likely contributes to the maintenance of variation at B4galnt2 in wild mouse populations." (PMID 26133982, 2015). "Furthermore, vascular endothelial B4galnt2 expressing animals (RIII+) exhibited increased Il-6 expression (Z = -1.932, P = 0.0528), but decreased LCN-2 production, suggesting a role for vascular B4galnt2 expression in the host immune response to intestinal infection." (PMID 26133982, 2015).
melanoma (2 papers, 2022 to 2023). A malignant, usually aggressive tumor composed of atypical, neoplastic melanocytes. "In conclusion, we reported the association of HRGs with patient prognosis in melanoma and screened for novel gene signatures, including FBP1, NDRG1, GPI, IER3, B4GALNT2, BGN, PKP1, and EDN2." (PMID 37422626, 2023).
Salmonella Infections (2 papers, 2017 to 2019). Infections with bacteria of the genus SALMONELLA. "Moreover, Turicibacter could reduce susceptibility to Salmonella infection in mice deficient in the expression of blood group glycosyltransferase β-1,4-N-acetylgalactosaminyltransferase 2 (B4galnt2), which is responsible for the synthesis of blood antigens." (PMID 31362781, 2019).
ulcerative colitis (2 papers, 2021). An inflammatory bowel disease involving the mucosal surface of the large intestine and rectum. "Recently, an association of B4GALNT2 mRNA with ulcerative colitis, an inflammatory pre-neoplastic condition, has been reported." (PMID 34771437, 2021). "The B4GALNT2 transcript was found to be more expressed in long-duration, compared with short-duration ulcerative colitis cases." (PMID 34771437, 2021). "In long- and short duration ulcerative colitis, GUCA2B displays a differential expression in parallel with B4GALNT2." (PMID 33919332, 2021).
bleeding disorder (1 paper, 2017). "Interestingly, there is variation in the localization of B4galnt2 expression and GalNAc residue localization across wild populations of mice, which is thought to be due to balancing selection between susceptibility to gut pathogens and a bleeding disorder." (PMID 28874116, 2017).
colitis (1 paper, 2015). Inflammation of the colon. "Using an established model for Salmonella Typhimurium induced colitis, we found that loss of B4galnt2 expression in the intestinal epithelium decreases susceptibility to infection." (PMID 26133982, 2015). "To test the hypothesis that expression of intestinal B4galnt2 glycans influences host susceptibility to enteric pathogens, we used an established model for S. Typhimurium induced colitis." (PMID 26133982, 2015).